PLK1 (polo like kinase 1)
Diseases named in the same sentence as PLK1 in open-access papers (continued):
Sharing a sentence is not in itself a finding about the gene and the disease.
cancer (continued). "Compared with the abundant evidence of PLK1 inhibitors against several cancer types, the evidence regarding PLK2 inhibitors is limited." (PMID 32878237, 2020). "Normalization of DNMTs and UHRF1 to other markers of cancer cell proliferation, including PLK1 and BUB1, provided similar results as seen with MKI67 normalization." (PMID 32213861, 2020). "The improvement of the basic biology of PLK1 have helped us to deeply understand its function in regulating the cell cycle, and various observations on the upregulation of PLK1 in human cancers also provided researchers a new anti-tumor target." (PMID 33176854, 2020). "STAT3 and PLK1 are known to control each other's transcription in a positive feedback loop resulting in cancer cell survival, proliferation and resistance to apoptosis." (PMID 32231398, 2020). "ERCC6L knockdown was demonstrated to result in downregulation of PLK1 which serves an important role in the control of the proliferation and cell cycle in cancer cells." (PMID 32703154, 2020). "Despite an intensive use of Ki-67 and Plk1 for an immunohistochemical analysis of a huge variety of cancer entities, their prognostic potential in early-stage OC remains elusive." (PMID 33117692, 2020). "The PLK1 pathway also participates in the regulation of cell mitosis and acts as an oncogenic factor to promote cancer development." (PMID 32213663, 2020). "Polo-like kinase 1 (PLK1) is overexpressed near ubiquitously across all cancer types and dysregulation of this enzyme is closely tied to increased chromosomal instability and tumor heterogeneity." (PMID 33066048, 2020). "Clinically, PLK1 has been raised as a target for cancer treatment because of its connection with malignancy and advanced cancer development in NSCLC." (PMID 31548612, 2020). "Polo-like Kinase 1 (PLK1) is often up regulated in cancers and it regulates chromosomal instability extensively." (PMID 33066048, 2020). "Telomerase inhibition in anticancer therapies has been widely pursued and trialed, as it is aimed for a target that, similarly to PLK1, is distinguished in cancer cells from normal cells almost ubiquitously." (PMID 33066048, 2020). "This is somewhat surprising, since the rationale for targeting PLK1 is strongly supported in theory by the accumulated preclinical data and our understanding of its role in cancer cells." (PMID 33066048, 2020). "The function of PLK1 in sustaining the proliferative capacities of cancer cells has been previously reported." (PMID 32268485, 2020). "Accordingly, as a key regulator of the cell cycle, PLK1 is also overexpressed in various cancer types and functions in tumor initiation, progression, and chemoresistance." (PMID 33106477, 2020). "Among the ZNF143-targeted cell cycle-associated kinases, both PLK1 and Aurora kinase B (AUPKB) were overexpressed in a large variety of cancers." (PMID 32076462, 2020). "PLK1 is a mitotic kinase near-ubiquitously overexpressed in cancer, with a key multifaceted role in the maintenance of chromosomal stability." (PMID 33066048, 2020). "Both Plk1 and Plk4 have been investigated as potential targets in anticancer therapies as inhibition of their activity induces cell death in cancer cells." (PMID 32060361, 2020). "Early findings that PLK1 is highly expressed in cancer have driven an exploration of its functions in metastasis." (PMID 31548612, 2020). "Some of them, focused on the G2/M DNA damage checkpoint (e.g., PLK1, WEE1 G2 checkpoint kinase (WEE1) or telangiectasia mutated kinase (ATM)) are being investigated clinically in many cancers with promising results." (PMID 32268485, 2020). "PLK1 overexpression has been detected in a multiple human tumors, and its expression degree is related with increased proliferation of cancer cells in patients and with poor prognosis." (PMID 32518522, 2020). "Errant PLK1 activity in cancer also results in impaired apoptotic pathways and PLK1 overexpression actively promotes tumor formation after induction of DNA damage." (PMID 32805721, 2020).
cancer (continued). "Out of the five members of the Plk family, Plk1 and Plk4 are considered as promising targets in cancer therapies due to their important functions as kinases during the cell cycle of tumor cells." (PMID 32060361, 2020). "This consistency across tumor types combined with minimal expression in normal tissues and its extensive role in chromosomal instability highlights strong PLK1 potential as a target for a tumor-agnostic cancer therapy." (PMID 33066048, 2020). "PLK1 controls the development of cancer through a variety of mechanisms, including mitosis, cytokinesis, DNA replication, and cell survival." (PMID 32518522, 2020). "The identification of SDL interactions of PLK1 in the processes promoting CIN, as discussed in this review, is expected to provide novel options for developing effective anti-cancer therapies that would bypass dangers associated with its direct inhibition." (PMID 33066048, 2020). "Minor progress has been made via high-throughput drug screens in several tumors including cyclin-dependent kinase 1/2 (CDK1/2)-, polo-like kinase 1 (PLK1)-, and WEE1-mutated cancers." (PMID 32883316, 2020). "Plk1 is overexpressed in many cancers and is thus considered an important target in cancer therapeutics." (PMID 32810142, 2020). "Increased expression of PLK1 has been observed in several types of malignant tumors and has been shown to be correlated with lower survival rates among solid tumor patients." (PMID 32486290, 2020). "The first chemical inhibitors gained attention for their anti-cancer effects shortly after, albeit the first PLK1 inhibitors were of a broader specificity." (PMID 33066048, 2020). "On the other hand, in the studies showing that Plk1 play as a tumor suppressor, there is also data showing that Plk1 overexpression confers good prognosis to certain cancer subtypes." (PMID 30862113, 2019). "USP7 and PLK1 have strong clinical relevance, being overexpressed in tumor cells in a many cancer types." (PMID 31730000, 2019). "To test PASTMUS strategy in mapping functional elements of proteins, we selected three genes (ANTXR1, CSPG4, and HBEGF) encoding bacterial toxin receptors and three genes (HPRT1, PLK1, and PSMB5) encoding cancer drug targets." (PMID 31842968, 2019). "PLK1, an essential kinase involved in the cell cycle, was chosen as a therapeutic target gene because its silencing can induce apoptosis in various cancer cells." (PMID 31019193, 2019). "PLK1 has been considered a bona fide cancer target, and PLK1 inhibition results in aberrance of mitotic progression." (PMID 31730000, 2019). "Chemical inhibitors targeting mitotic regulators, such as Aurora kinases, CENP-E and PLK1, are being developed as anti-cancer drugs." (PMID 30655516, 2019). "Outside the cancer field, the role of PLK1 in normal mitotic cells especially stem cells are poorly understood." (PMID 31393265, 2019). "In humans, PLK1 is often overexpressed in a broad spectrum of cancers and its overexpression correlates with prognosis." (PMID 31437238, 2019). "PLK1 plays a role in centrosome disjunction and separation and is highly expressed in human cancers." (PMID 31159515, 2019). "It has been previously reported that CGs such as bufalin, glucoevatromonoside, digitoxin, and ouabain induce cell cycle arrest at the G2/M phase by deregulating the expression of polo-like kinase 1 (Plk1) expression in cancer cells." (PMID 32010609, 2019). "Inhibition of PLK1 by small interfering RNA or pharmacological inhibitors exerts antitumor effect in vitro and in vivo, providing strong preclinical and clinical support for the use of PLK1 inhibitors in cancer therapy." (PMID 31393265, 2019). "Data indicate that overall, pediatric cancer cell lines show some but variable sensitivities to PLK1 inhibition." (PMID 31824851, 2019).
cancer (continued). "The fact that this CIN derived from Plk1 activity alterations can promote or stop cancer progression demonstrates that the role of Plk1 in tumorigenesis is much more complex to understand, and deserves further attention." (PMID 30862113, 2019). "In pediatric cancer, PLK1 is over-expressed 2.6 fold in childhood acute lymphoblastic leukemia and 1.5 fold in rhabdomyosarcoma, and is highly expressed in pediatric Ewing sarcoma, neuroblastoma, and osteosarcoma." (PMID 31741706, 2019). "Polo-like kinase 1 (PLK1) is a gene that is vital in cell division and DNA damage response and was found to be expressed in actively dividing cancer cells." (PMID 31064156, 2019). "Elevated levels of Plk1, a crucial kinase during mitotic cell division, have been described in multiple cancer types, including NSCLC, with high expression levels being associated with poor survival." (PMID 31795121, 2019). "The fact that Plk1 is overexpressed in tumors, and that Plk1 inhibition is an efficient way to stop cancer cell proliferation positioned PLK1 as a promising cancer target." (PMID 30862113, 2019). "Pharmacological inhibition or small interfering RNA-mediated depletion of PLK1 in cancer cells results in activation of the apoptotic pathway." (PMID 30976076, 2019). "Polo‐like kinase 1 (Plk1) is a serine–threonine protein kinase that is overexpressed in cancer cells and plays a major role in the regulation of G2–M transition and response to DNA damage." (PMID 31040125, 2019). "PLK1 is highly expressed in several cancer types, and thus represents a druggable target in cancer therapeutics." (PMID 31393265, 2019). "And as a result, a cohort of APCCdh1 substrates, including Plk1, Cdc6, Skp2, cyclin A, are eliminated, which eventually helps to amplify and sustain the anti-cancer function of these inhibitors." (PMID 31420536, 2019). "Plk1 is a very well-known mitotic kinase, intimately related to cancer events since its description in mammals." (PMID 30862113, 2019). "FOXM1 and PLK1 are cooperatively overexpressed in various cancers and identified as potential therapeutic targets." (PMID 31185958, 2019). "In past decades, we have gathered a large number of reports showing that Plk1 is indeed overexpressed in many different cancer types and that this overexpression is crucial for the cancer progression." (PMID 30862113, 2019). "Due to the clinical relevance between PLK1 expression and cancer malignancy, PLK1 has been investigated as a target for anticancer drug development." (PMID 31100782, 2019). "Both USP7 and PLK1 were overexpressed in taxane-resistant cancer cells, and negatively correlated with the MP scores in tumor tissues." (PMID 31730000, 2019). "The tumor suppression capacity of Plk1 has also been shown in other cancer models such as colorectal cancer." (PMID 30862113, 2019). "Plk1 has strong clinical relevance, as it is considered a bona fide cancer target, it is found overexpressed in a large collection of different cancer types and this tumoral overexpression often correlates with poor patient prognosis." (PMID 30862113, 2019). "Two experimental studies correlate the reduced levels of Plk1 with cancer appearance due to the induction of aneuploidy and CIN." (PMID 30862113, 2019). "The depletion of PLK-1 gene expression was directly promoted G2/M phase arrest in the human cancer cells." (PMID 30733560, 2019). "PLK1 is overexpressed in several carcinomas, and its expression correlates with tumor proliferation and malignancy." (PMID 31100782, 2019). "The cancers with higher PLK1 expression levels tended to have lower immune activities, such as lower HLA expression and decreased B cells, NK cells and tumor-infiltrating lymphocytes infiltration." (PMID 30631355, 2018).
cancer (continued). "Inhibition of Plk1 by siRNA or small molecule inhibitors has resulted in cell cycle arrest in metaphase and the induction of apoptosis in cancer cell lines." (PMID 29402316, 2018). "Up to this point, it is interesting to note that in both cell lines, MP-HX downregulated all six top-ranked genes (PLK1, MCM2, MCM3, MCM7, MCM10 and SKP2) that were proposed to be cancer-associated (Wu, Zhu & Zhang, 2012)." (PMID 30042885, 2018). "The GDSC data analysis showed that the PLK1 expression negatively correlated with the HLA activity in cancer cell lines (Spearman correlation, R=-0.12, P=2.0∗10−4)." (PMID 30631355, 2018). "Taken together, these results suggest that the PLK1 expression likely inhibits the HLA activity in cancer." (PMID 30631355, 2018). "To investigate the role of PLK1 in cancer cells with CIN, we expressed in both cell lines a truncated APC protein containing amino acids 1-750 of APC, hereafter named APC-ΔC, thus removing all β-Catenin regulatory sequences." (PMID 29549256, 2018). "The gene expression levels of cyclin B1 (CCNB1), cyclin B2 (CCNB2), Aurora A (AURKA), Aurora B (AURKB), and PLK-1 (PLK1) were increased from stages 1 to 4; however, the genes for D-type cyclins were expressed in a stable manner across the cancer stages." (PMID 30235818, 2018). "As expected, the TCGA data analysis showed that the PLK1 expression levels strongly correlated with the cell cycle activity in a positive direction in all 33 cancer types." (PMID 30631355, 2018). "The overall survival of the animals significantly increased compared to controls, suggesting PLK1 inhibitors would be promising cancer therapeutics in clinical trials." (PMID 30414309, 2018). "In agreement with our previous findings in U2OS cancer cells, PLK1 target phosphorylation remained undetectable during active DNA replication and only appeared when the bulk of PCNA foci disappeared." (PMID 30008317, 2018). "Strong positive correlations between the metastasis of human cancer and the up-regulation of Plk1 have been reported; however, none of these studies demonstrated the exact functional mechanism by which Plk1 is involved in metastasis." (PMID 29191835, 2018). "PLK1 is a master regulator of cell cycle, and its overexpression is oncogenic in various cancer types." (PMID 30631355, 2018). "For another, the serine/threonine kinase PLK1, governs several mitotic steps, especially mitotic exit and entry into mitosis, keeping cancer cells from genome instability." (PMID 29954437, 2018). "This is the first study to report a PLK-1 inhibitor (GSK) encapsulated in a nanocarrier for cancer applications." (PMID 30304810, 2018). "Among Polo-like kinases, Plk1 is considered an interesting target for cancer therapy due to the requirements for its kinase activity during cell division in tumor cells." (PMID 30069007, 2018). "To date, PLK1-siRNA is one out of four RNAi-based drugs that have been evaluated in early clinical trials for cancer therapy through systemic administration." (PMID 29295989, 2018). "Altogether, these data suggest that elevated PLK1 expression tends to inhibit immune cell infiltration and antitumor immunity in a number of cancer types." (PMID 30631355, 2018). "In fact, a substantial number of studies have revealed that PLK1 was overexpressed in a wide variety of cancers, and its overexpression correlated with unfavorable prognosis of cancer patients." (PMID 30631355, 2018). "We rationalized to combine miR-34a and PLK1-siRNA in order to attack distinct molecular defects in this cancer while inhibiting MYC, a common target of PLK118 and miR-34a19." (PMID 29295989, 2018).
cancer (continued). "Despite many trials using Xenograft models for the evaluation of Plk1 in cancer development, to our knowledge we have analyzed here for the first time the role of Plk1 in a transgenic, murine cancer model." (PMID 29549256, 2018). "TAK-960 is an ATP-competitive Plk1 inhibitor that has demonstrated efficacy across a broad range of cancer cell lines, including CRC." (PMID 29402316, 2018). "Altogether, these results suggest that the PLK1 upregulation inhibits antitumor immunity via enhancing the cell cycle activity in cancer." (PMID 30631355, 2018). "On the other side, elevated tumor immunity likely increased the sensitivity of cancer cells to PLK1 inhibitors." (PMID 30631355, 2018). "In the drug sensitivity validation, some cells are sensitive to the drug target PLK1, which indicates that PLK1 can participate in various cancers by forming SL gene pairs with many cancer genes." (PMID 29855504, 2018). "This experiment verified the results from bioinformatics analysis that the PLK1 expression inversely correlated with the HLA activity in diverse cancer types." (PMID 30631355, 2018). "Plk1 is also a very attractive target for cancer therapy because it is overexpressed in most tumor cells and tissues and poorly or not expressed in untransformed cells." (PMID 29541386, 2018). "We used the PLK1 inhibitor (BI2536) to treat cancer cell lines and compared expression levels of MHC class I (HLA-A, HLA-B, HLA-C, B2M, and TAP1 genes and their protein products) between the pre- and post- treated cell lines." (PMID 30631355, 2018). "It is rational in that higher levels of B cells, NK cells, or TILs are associated with lower levels of PLK1 that would need lower concentrations of PLK1 inhibitors to inhibit cancer cell proliferation." (PMID 30631355, 2018). "Markedly, the CTA genes ATAD2, CEP55, FANCA, KIF2C, NUF2, OIP5, and PBK had significantly positive expression correlations with the PLK1 expression in 30 cancer types (Pearson correlation, FDR<0.1)." (PMID 30631355, 2018). "Our bioinformatics analyses showed that PLK1 expression tended to inhibit antitumor immunity as the cancers with higher PLK1 expression levels often had lower HLA expression levels and TILs infiltration." (PMID 30631355, 2018). "KLHLs are thus intriguing genes for cancer as they can directly influence the degradation of therapeutically relevant cell cycle regulators such as Aurora Kinase, PLK1, or CDK1." (PMID 30647843, 2018). "Anti-PLK1 antibodies and small interfering RNA (siRNA) treatment-based studies have shown the essential role of PLK1 in the mitotic progression of cancer." (PMID 29765534, 2018). "One of these compounds, BI2536, a PLK1 specific inhibitor, has shown antitumor and cytotoxic effects in several cancers." (PMID 29765534, 2018). "The potential of combining PLK1 inhibition with immunotherapy for cancer treatment is worthy of exploration." (PMID 30631355, 2018). "In one specific example, we focused on the measured inhibitions of PLK1 activity, responsible for establishing the mitotic spindle and that is frequently hyper‐activated in cancer." (PMID 30104419, 2018). "Remarkably, high levels of PLK1 have been correlated with poor patient prognosis in different types of cancer including NSCLC, colon cancer and hepatoblastoma." (PMID 29899826, 2018). "In conclusion, we described herein for the first time a specific cleavage of Plk1 by caspase 3 following treatment of cancer cells with ATP-competitive inhibitors of Plk1." (PMID 29541386, 2018). "Polo-like kinase 1 (Plk1) is overexpressed in a wide spectrum of human tumors, being frequently considered as an oncogene and an attractive cancer target." (PMID 30069007, 2018). "Because miR-100 has been reported to target Plk1 in certain cancer cells, we assessed the effects of miR-100 on Plk1 expression in smooth muscle cells." (PMID 30135525, 2018).